TMEM128 (transmembrane protein 128)
Synonyms: MGC13159
Tractability: Antibody: UniProt predicts a signal peptide or a membrane-spanning region.
Gene: Protein-coding gene on chromosome 4 (4,235,541 to 4,248,239, reverse strand). Ensembl gene ENSG00000132406.
Subcellular location: Membrane
Gene Ontology:
Molecular function: protein binding
Cellular component: membrane
Genetic constraint (gnomAD): Loss-of-function variants: 15 observed, 14.81 expected, observed/expected ratio (o/e) 1.01, 90% interval 0.68 to 1.55. The synonymous counts are far from expectation, so gnomAD's model fits this gene poorly and the ratio says little. Missense variants: 227 observed, 182.61 expected, observed/expected ratio (o/e) 1.24, 90% interval 1.12 to 1.39. Synonymous variants: 89 observed, 67.78 expected, observed/expected ratio (o/e) 1.31, 90% interval 1.11 to 1.57.
Homologues: Orthologues: chimpanzee TMEM128 (99% identical), macaque TMEM128 (95% identical), dog TMEM128 (83% identical), pig TMEM128 (82% identical), mouse Tmem128 (81% identical), rabbit TMEM128 (81% identical), guinea pig TMEM128 (81% identical), rat Tmem128 (79% identical), tropical clawed frog tmem128l (54% identical), tropical clawed frog tmem128 (51% identical), zebrafish TMEM128 (33% identical).
Diseases named in the same sentence as TMEM128 in open-access papers:
TMEM128 is named in the same sentence as 1 disease in open-access papers, as found by Europe PMC text mining. Sharing a sentence is not in itself a finding about the gene and the disease.
Sepsis (1 paper, 2025). Sepsis is defined as life-threatening organ dysfunction caused by a dysregulated host response to infection.